EGFR (epidermal growth factor receptor)
Diseases named in the same sentence as EGFR in open-access papers (continued):
Sharing a sentence is not in itself a finding about the gene and the disease.
cancer (continued). "In radiation-tolerant OSCC cells, BTK may be involved in the EGFR/AKT/mTOR signaling pathway and increase the drug sensitivity of cancer cells after radiotherapy." (PMID 33640903, 2021). "Immunohistochemistry of feline OSCC tissue confirmed that the epidermal growth factor receptor (EGFR) is a relevant target with expression in cancer cells and not in the surrounding stroma." (PMID 36405501, 2021). "Patients with right hemi colic cancers do not benefit from anti-EGFR therapy irrespective of RAS status." (PMID 33920536, 2021). "In contrast, the compound only weakly inhibited the proliferation of cancer cells with low or without EGFR expression." (PMID 34925034, 2021). "EGFR transmits signals from cytoplasm to nucleus through RAS/RAF/MEK/ERK/MAPK, PI3K/PTEN/AKT/mTOR, and some other intracellular signaling pathways which participate in regulating cancer cell proliferation, invasion, and angiogenesis." (PMID 35111681, 2021). "In TNBC and other cancers, the ID oncogenic transcripts foster diverse cancer-related events, including EMT, signaling (e.g., EGFR/TGF-beta, K-Ras, WNT, STAT3, PI3K/Akt, OCT-4/ID1/NF-kappaB), where ID genes are a target of many anticancer drugs, including vinblastine." (PMID 34299315, 2021). "In addition, several mechanisms of cancer development are related to ANO1, such as the EGFR-mediated AKT/SRC/ERK1/2 or Ras-Raf-MEK-ERK1/2 pathways; nonetheless, the underlying mechanism is unclear in NSCLC." (PMID 34281152, 2021). "Moreover, Diego A. Pedroza proved that PGRMC1 altered the PI3K/AKT/mTOR and EGFR signaling in TNBC cells, playing a crucial role in regulating the growth of cancer cells." (PMID 34746100, 2021). "The differences in the results might be due to environmental, genetical, geographical factors, gender distribution, the initial response to the EGFR-TKI treatment, and the progression pattern of the cancer." (PMID 34963835, 2021). "These functional observations are also in line with our finding that BRAF/EGFR-mutant lung tumors are recurrently found across different cancer centers, indicating a basis for the co-existence of BRAF/EGFR mutations without selection pressure." (PMID 34921211, 2021). "In addition, cancer pair COAD and UCEC depends on components of the EGFR pathway at similar frequencies (Wormald, Milla & O’Connor, 2013)." (PMID 33505797, 2021). "Therefore, conjugation of fluorescent dyes to antibodies or to peptide sequences directed at EGFR and VEGFR receptors, as well as to tyrosine kinase inhibitors (TKIs), is an effective strategy currently used in medical imaging and cancer treatment." (PMID 33670650, 2021). "Bi‐EGF‐IT was tested for in vitro binding affinity, cytotoxicity, and specificity using 14 human EGFR‐expressing HNSCC cell lines and three human EGFR‐negative cancer cell lines." (PMID 33540470, 2021). "Using PD153035, an EGFR tyrosine kinase inhibitor, we demonstrated that targeting EGFR did not affect the proliferation or cell death of cancer cells in the 3D system." (PMID 34885111, 2021). "Recently, studies in EGFR-positive cancer cells have shown that sustained activation of STAT3, due to enhancement of its binding to FGFR1, plays a key role in the acquisition of resistance to EGFR inhibitors." (PMID 34830951, 2021). "EGFR signaling activates NF-κB via the IKK complex and IκBα, whereas inhibition of NF-κB is a common feature of several members of the cardenolide glycoside family related to cancer cell mitotic arrest and apoptosis." (PMID 34025398, 2021). "In addition, MET is a known favorable interacting partner in cancer, and evidence indicates that MET induces resistance to anti-EGFR drugs in NSCLC28." (PMID 33603128, 2021). "PD153035 treatment did not alter the cancer cell surface expression of EGFR in the HCTT16 or the HCT116 + THP1 groups." (PMID 34885111, 2021).
cancer (continued). "The ErbB family members ErbB1 (epidermal growth factor receptor (EGFR)) and ErbB2 (human epidermal growth factor receptor 2 (HER2)) are intensively studied receptor tyrosine kinases (RTKs) with fundamental roles in cancer." (PMID 33128042, 2021). "The anti‐EGFR antibody conjugated on colloidal GNP specifically and homogeneously binds to the surface of the cancer cells with 600% greater affinity than with the non‐cancerous cells as evident by Surface Plasmon Resonance Imaging and Spectroscopy in two malignant oral epithelial cell lines." (PMID 34694743, 2021). "The ETAR antagonists ZD4054 and atrasentan used combined with the EGFR inhibitor gefitinib and the monoclonal HER2-specific antibody trastuzumab, respectively, present a powerful capacity to repress the proliferation and invasion of cancer cells." (PMID 34943797, 2021). "EGFR initiates a signaling cascade that leads to DNA synthesis and cell proliferation; and EGFR and PI3K initiate malignant transformation of cancer cells by activating other pathways such as Myc and Rb-E2F, which in turn leads to the formation of cyclinD/Cdk4 and cyclinE/Cdk2 complexes." (PMID 34658851, 2021). "ECD KD markedly reduced the levels of ErbB2 mRNA but not the levels of EGFR mRNA, even in a cancer cell line with EGFR overexpression." (PMID 33941617, 2021). "Together, our findings indicate that EGFR plays an important role in the regulatory network and pathways of MYCN and therefore may represent an attractive therapeutic target for cancer treatment." (PMID 33968733, 2021). "Dysregulation in activity of EGFR, IGF‐1R, and VEGFR is highly correlated with a lot of cancers." (PMID 33783993, 2021). "﻿In response to anti-cancer drugs, WM_Score highly negatively correlated (drug sensitive) with drugs which targeted oncogenic related pathways, such as MAPK, EGFR, and mTOR signaling pathways, positively correlated (drug resistance) with drugs which targeted in apoptosis and cell cycle." (PMID 33557837, 2021). "Further, miR-145 significantly suppressed EGFR expression and inhibited cancer cell growth compared with negative control miRNA in A549 NSCLC cells." (PMID 34830377, 2021). "In conclusion, we show that signaling downstream of the EGFR differs between cell lines, but β4 or its tyrosine phosphorylation does not affect the signaling of the EGFR, neither in cancer cells nor in non-cancerous epithelial cells." (PMID 33883672, 2021). "Furthermore, autophagy was induced by EGFR siRNA in cancer cells 14, and KRAS acts downstream of EGFR." (PMID 33995628, 2021). "Due to the scarce literature data on EGFR SNPs in RT- and CHT-treated cancer patients, we were unable to fully relate our findings to the observations of other authors, which may have affected the interpretation of the results." (PMID 34070597, 2021). "According to immunohistochemical staining analysis, normal tissues did not express EGFR protein, and cancer tissues exhibited a 60% positive staining for EGFR." (PMID 34830377, 2021). "Affinity extraction demonstrated that rSLURP-1 in A549 cells forms a complex not only with α7-nAChR, but also with PDGFRα and epidermal growth factor receptor (EGFR), which are known to be involved in regulation of cancer cell growth and migration and are able to form a heterodimer." (PMID 34595181, 2021). "In addition, sEVs containing secretory EGFR derived from GC cells effectively activate hepatocyte growth factor, which in turn binds to c-MET receptors on migrating cancer cells to promote the homing of metastatic cancer cells." (PMID 33926452, 2021).
cancer (continued). "The rationale beyond this “rechallenge” strategy is that, after disease progression to first line EGFR-based chemotherapy, a treatment “holiday” from anti-EGFR drugs results in RAS mutant cancer cell decay, restoring the sensitivity of cancer cells to cetuximab or panitumumab." (PMID 33920531, 2021). "Proteoglycans are mainly produced by the cancer-associated fibroblasts (CAFs) in the stroma and play a role in intercellular and ECM interactions via activation of receptor tyrosine kinases (EGFR, FGFR, IGF1R, INSR) on the cancer cells regulating the proliferation and survival cascaded." (PMID 34851463, 2021). "HER2 breast cancer is one of the most frequently occurring types of cancer worldwide, and one of the potential biomarkers for its detection could be human epidermal growth factor receptors (HER/erbB), which is involved in normal growth and differentiation." (PMID 33494499, 2021). "Therefore, we feel that the binding relationship between EGFR and miR-222-5p in HCC and other cancers merits further, more detailed investigation." (PMID 33952719, 2021). "Although ligand binding is needed for EGFR dimerization and activity in normal as well as cancer cells, ligand binding is not necessary in some cancer types." (PMID 33670650, 2021). "The majority of the non-luminal epithelial cancer cells were basal-like (B1) or mesenchymal-like (M1–M3), and had the highest expression of CD49f and EGFR." (PMID 33790302, 2021). "Moreover, deltarasin does not inhibit the growth of cells transformed with the oncogenic mutant B-Raf or the overexpressed epidermal growth factor receptor (EGFR), suggesting that PDE6δ inhibitors are effective against K-Ras–dependent cancer cells." (PMID 34222333, 2021). "EGFR and VEGFR overexpression is frequently found in several types of tumors, including breast, lung, colon, and ovarian, and therefore it is a very attractive therapeutic and imaging target for cancer treatment research." (PMID 33670650, 2021). "Through EGFR control, USP17 and USP18 were shown to play a role in cancer cell survival." (PMID 34577547, 2021). "Our analysis revealed that cancer cells with decreased NF2 expression display high sensitivity to DNA synthesis inhibition (Cytarabine, Oxaliplatin, and 5-Fluorouracil) and epidermal growth factor receptor (EGFR) targeted therapies (Gefitinib and Lapatinib)." (PMID 33805359, 2021). "EGFR is frequently overexpressed in HNSCC and a variety of other cancers." (PMID 34359613, 2021). "Similarly, in FGFR2-positive GC, resistance to AZD4547 was abolished by EGFR, HER3, or MET inhibition, indicating that these other RTKs are responsible for cancer cell resistance to FGFR inhibition." (PMID 34830951, 2021). "In previous clinical research, EGFR TKI (Epidermal growth factor receptor tyrosine kinase inhibitor) did not have sufficient therapeutic effects on drug-resistant cancers, even though EGFR expression was upregulated." (PMID 33498235, 2021). "Hence EGFR and HER2 are feasible targets for cancer therapy, and agents targeting these molecules have been FDA-approved for HNSCC treatment, demonstrating increased response rates and increased overall survival when combined with standard therapy." (PMID 34298667, 2021). "Likewise, EGFR/Her1 and HER2 have been found on EVs from the cancer cell lines SkBr2 and BT474 that both overexpress HER2." (PMID 33207034, 2021). "The first clinical evidence for the involvement of EGFR in neuropathic pain was observed in cancer-induced neuropathic pain and later expanded to non-cancer patients." (PMID 34054523, 2021). "Among the 72 samples, 32 contained driver mutations in well-known cancer genes in NSCLC, such as EGFR (n = 26; E709G, T790M, L858R and non-frameshift deletions of exon 19), and PIK3CA (n = 4; E542K and G1049R)." (PMID 33407425, 2021).
cancer (continued). "EGFR was confined to the cancer cells arranged in neoplastic nests and absent in the surrounding stroma, which, in the context of NB-PDT, will most likely result in no damage to the structural component of the oral mucosa." (PMID 36405501, 2021). "In addition, various oncogenic pathways have been reported to affect expression of HLA-I in cancer, including mitogen-activated protein kinase (MAPK) and epidermal growth factor receptor (EGFR)." (PMID 34458148, 2021). "Overexpression of DBH-AS1 via miR-223-3p/EGFR/AKT axis could enhance the glycolytic activity and reduce cancer progression." (PMID 33768092, 2021). "We found that the IC50 values of several anti-cancer drugs decreased in the high-TRPV4 group, including sapitinib (an EGFR inhibitor) and selumetinib (a MEK1/2 inhibitor), indicating that patients exhibiting high TRPV4 expression levels are relatively sensitive to these anti-cancer drugs." (PMID 34262942, 2021). "Thus, the signaling of thyroid hormone–integrin αvβ3 induces transcription of the EGFR, modulates functions of EGFR and IGF-IR, and stimulates cancer cell progression." (PMID 34359854, 2021). "Drugs with targets such as EGFR, ERBB2, MTOR, PARP2, AURKB, MAP2K1 and PLK1 share more similar profiles, which indicates that the inhibition of these targets has specific effects on the in vitro viability and proliferation of cancer cells." (PMID 33795761, 2021). "Nevertheless, the size effect of AuNPs on cytotoxicity and the phenotypic evaluation of EGFR-overexpressing cancers have not been well documented." (PMID 33499047, 2021). "Besides, perifosine also participates in mitogen-activated protein kinase (MAPK), nuclear factor-κB and autography signal pathway, and targets epidermal growth factor receptor (EGFR) and death receptor (DR4/DR5) to inhibit the growth of cancer cells." (PMID 34322387, 2021). "EGFR and VEGFR are important targets for cancer diagnosis and treatment." (PMID 33670650, 2021). "When the same combination therapy was used in the EGFR-negative cancer cell line MCF-7, only around 10% of cancer cells underwent apoptosis." (PMID 34683944, 2021). "Accumulating evidence has demonstrated that down-regulation of miR-145 significantly promotes cancer progression: conversely, up-regulation of miR-145 significantly inhibits cancer progression by targeting cellular pathways, such as Wnt/β-catenin, PI3K/AKT and EGFR." (PMID 34946098, 2021). "Many mutants of RAB31 have been detected in various types of human cancer, and we were very curious to test whether any RAB31 mutant may also induce this localization of EGFR to CD63-positive MVEs." (PMID 32958903, 2021). "Targetable EGFR mutations were found in 89.3% (25/28) of inverted sinonasal papilloma (ISP) and in 60% (6/10) of ISP-associated carcinomas." (PMID 34885191, 2021). "In EGFR overexpressing A431 epithelial carcinoma lacking endogenous AnxA6, restoration of AnxA6 expression promoted PKCα-mediated threonine 654-EGFR phosphorylation, which inhibited EGFR tyrosine kinase activity, cell growth, migration and invasion." (PMID 33810523, 2021). "Though the MAPK inhibitor and EGFR inhibitor blocked the invasion of cancer cells in response to NF and CAF, these inhibitors did not block scattering in 2-D cell cultures." (PMID 32731484, 2020). "Binding of the anti-EGFR sdAbs to the EGFR extracellular domain may prevent EGF from binding to EGFR, or homophilic cancer cell–cell adhesion through cell surface EGFR interaction." (PMID 33023595, 2020). "MET, EGFR and STAT3 function as oncogenes in many types of malignant tumors including NSCLC." (PMID 33318313, 2020). "In light of significance of TGFβ1, SHH, EGFR, and LEF‐1 in the proliferation and migration of cancer cells, we examined the differential expression of those proteins in the cell lysis solution of NFs and CAFs and paid our attention to the different expression of SHH." (PMID 32030915, 2020).
cancer (continued). "Patients with other types of cancer prior to or within 1 year after the diagnosis of NSCLC (n = 278), those aged < 20 years, and those with negative or lack of EGFR mutations analysis (n = 154), were excluded from the analysis." (PMID 32917914, 2020). "c-Src inhibitor-1 efficacy in overcoming resistance to EGFR inhibitors was also reported in HER2+ gastric and biliary tract tumors: cancer cells resistant to the anti-HER2 antibody trastuzumab showed higher c-Src and FAK phosphorylation levels, compared to sensitive cells." (PMID 32517369, 2020). "As several receptors, including EGFR, accumulate at the cell surface upon FEME inhibition, the possibility that blocking the pathway may potentiate anti-cancer therapies is exciting." (PMID 32589750, 2020). "EGFR and HER2 is the most promising therapeutic target for cancer." (PMID 34803263, 2020). "Although long-term AZD9291 treatment reduced TRIB3 and EGFR expression, it upregulated the expression and phosphorylation of STAT3, STAT5, and ERK1/2, suggesting the compensatory activation of other oncogenic pathways and induction of cancer stemness." (PMID 32694521, 2020). "Thus, MYLK-AS1 is an upstream regulator of EGFR/HER2, and acts as an oncogene, suggesting an additional target for cancer therapeutics." (PMID 32398965, 2020). "Besides α5β1 integrin, NRP1 co-interacts EGF with EGFR, and HGF with c-Met, and activates these pathways which participate in the proliferation of cancer cells." (PMID 32560565, 2020). "From the representative targeted therapy (EGFR-tyrosine kinase inhibitor, EGFR-TKI) to revolutionary immunotherapy, these therapeutics demonstrated that a better understanding of signaling pathways in cancer might benefit the development of novel therapeutics." (PMID 33134377, 2020). "EGFR and MMP9 have long been areas of research focus in cancer theranostics." (PMID 33007872, 2020). "An additional 141 cancer gene-related fusions detected by CICERO were not reported by the TCGA Research Network, 60 of which involved EGFR, one of the most frequently mutated genes in GBM." (PMID 32466770, 2020). "A total of 155 nodes, including 20 putative targets of HZJD decoction, were selected as core hubs based on topological importance and were closely associated with the regulation of cell proliferation, apoptotic process, and cancer-related pathways (AKT1, TNF, VEGFA, and EGFR) in CAG." (PMID 33354218, 2020). "Recent evidence of clinical trials highlights that the combination of two noncompetitive anti-EGFR antibodies can benefit patients with several cancers." (PMID 32336949, 2020). "Notably, the presence of major components of cancer signaling pathways such as PI3K/Akt, EGF/EGFR, RAS, JNK-MMP2/9, and estrogen makes lipid rafts a promising therapeutic target in anti-cancer therapy." (PMID 32664351, 2020). "Overall, our results with sapitinib, as well as those obtained with other quinazoline-based EGFR inhibitors, suggest that these compounds may have the potential to treat MDR in certain cancers that overexpress ABCB1 transporter." (PMID 33163405, 2020). "In the case of our PROSPECT-C trial, patients included in the study had access to anti-EGFR antibody treatment via the cancer drug fund (CDF) independent of the research biopsy findings, which meant that the research biopsies were of no direct patient benefit." (PMID 33014822, 2020). "In addition, the combination of EGFR-TKIs and FGFR-TKIs can be expected to be a better anticancer strategy than single TKI treatment of cancers with hyper activities of the EGFR and the FGFR." (PMID 33092268, 2020). "Activation and mutations of PI3 kinase (PI3K), mTOR, insulin-like growth factor (IGF-1), epidermal growth factor receptor (EGFR), and NF-κB pathways have all been identified in several human disorders, especially cancer." (PMID 33013390, 2020).